CXCR3 (C-X-C motif chemokine receptor 3)
Diseases named in the same sentence as CXCR3 in open-access papers (continued):
Sharing a sentence is not in itself a finding about the gene and the disease.
pancreatic cancer (continued). "A study by L. Gorchs and colleagues showed that CAFs down-regulate the expression of CXCR3 and CCR5 while upregulating CXCR4 expression in both 2D and 3D pancreatic tumor cultures, thereby inhibiting T cell tumor infiltration towards CXCL10." (PMID 39596815, 2024). "In pancreatic cancer, both CXCL10 and CXCR3 are expressed in tumor tissue, and their presence has been correlated with poor prognosis." (PMID 34328416, 2021). "In contrast, in pancreatic cancer, expression of both CXCL10 and CXCR3 in tumor tissue has been correlated with a poor prognosis mostly due to increased chemoresistance." (PMID 34328416, 2021). "In the absence of Cxcr3, splenic Klrg1 + GzmB + antitumor T cells wain while pancreatic cancer disseminates suggesting a role for these cells in eliminating circulating metastatic tumor cells." (PMID 36472588, 2023). "However, it needs to be noted that in pancreatic cancer expression of both CXCL10 and CXCR3 in tumor tissue have been correlated with metastasis and poor prognosis." (PMID 34328416, 2021). "Taken together these data suggest no significant role for T cells in CXCL10/CXCR3-driven development of pancreatic cancer." (PMID 34328416, 2021). "Despite not detecting a direct effect of IP-10 on CXCR3 signalling pathway, we decided to explore the possibility of a functional effect of IP-10 on pancreatic cancer cells." (PMID 25415223, 2014). "Our data also suggest that the ligands for the chemokine receptors CXCR3 (CXCL9, CXCL10, CXCL11) and CCR5 (CCL8) might affect the spatial distribution of CD8+ T cells in human pancreatic tumor tissues and enhance the relative T cell trafficking into tumor rich areas." (PMID 35954489, 2022).
diabetes (19 papers, 2013 to 2026). "CXCL9 is expressed in pancreatic β cells in response to pro-inflammatory cytokines, and deletion of the gene encoding its receptor CXCR3 accelerates diabetes in the NOD mouse." (PMID 37164005, 2023). "Similar results, although more controversial, were reported in CXCR3-deficient mouse models or upon antagonistic blockade of CXCR3, leading to delayed insulitis and diabetes onset." (PMID 33042009, 2020). "Some groups were able to effectively block the manifestation of diabetes in prone mice by blocking CXCR3-linked signaling." (PMID 24285974, 2013). "We show that antigen-experienced memory B cells in the circulation of donors with adult RO diabetes have comparable CXCR3 expression to that of ND donors, and that CXCR3 expression on pancreatic infiltrating B cells is lacking in young-onset individuals." (PMID 41273416, 2026). "Previous work demonstrated that T-bet+CXCR3+ Tregs were particularly effective at suppressing inflammation and played an important role in the inhibition of diabetes development in NOD mice." (PMID 40759576, 2025). "Research studies showed that ICOS ligand enhanced the homing of Tfh to the follicular region through the induction of C-X-C motif chemokine receptor 5 (CXCR5) as well as the chemotaxis of Treg to pancreas islet through CXCR3 in in early phase of diabetes." (PMID 37325657, 2023). "Further evaluation of the function of these CXCR3-expressing T cells after aCD3 treatment would be needed to definitively establish their role in diabetes pathogenesis." (PMID 37458220, 2023). "This discovery highlights the crucial role of ICOS from another perspective, as Cxcr3–/– NOD mice developed diabetes earlier than WT mice due to a decreased potential of these Cxcr3–/– Treg cells to migrate from pancreatic lymph nodes to β-islets." (PMID 32983168, 2020). "Our data showed that CXCR3 expression was reduced on memory B cells in individuals with long-standing diabetes." (PMID 29881878, 2018). "A clear reduction in MFI was observed for CXCR3 expression in individuals with long-standing diabetes vs healthy donors (p < 0.01 in Study A, p < 0.005 in Study B)." (PMID 29881878, 2018). "In line with previous studies, we also found that CXCR3 expression was reduced on CD3+ T cells in individuals with long-standing diabetes." (PMID 29881878, 2018). "Using intra-vital 2-photon microscopy in a mouse model of diabetes, we found that CXCR3 chemokine downregulated CD8+ T cell motility specifically within islets, promoting effector cell confinement to their target sites." (PMID 29904378, 2018). "Surprisingly, the CXCR3−/− NOD mouse developed diabetes even earlier, which turned out to be due to impaired navigation of Treg cells to the islets." (PMID 24285974, 2013). "Additionally, CXCR3 and CXCL10 are expressed in the inflammatory infiltrates of individuals with recent-onset (RO) diabetes although B cells expressing CXCR3 have been little studied." (PMID 41273416, 2026). "The MFI of each marker was then determined in each area for each sample, and unpaired Student’s t tests were used to compare area-specific differences in the expression of each marker between each diabetes group and healthy donors, with the main difference being found in CXCR3." (PMID 29881878, 2018). "Although the changes in CXCR3 expression were only significant in one of the newly diagnosed cohorts, they showed the same downward trend that we observed in the long-standing diabetes cohorts, along with the same significant increases in serum levels of CXCL10 and CXCL11." (PMID 29881878, 2018). "Statistical analysis of area 2, which comprised switched memory B cells with a CD21+CD24+CD27+CD38intCD95+IgD− phenotype, revealed that CXCR3 expression was reduced in individuals with long-standing diabetes relative to healthy donors in Study A (p < 0.05) and Study B (p < 0.005)." (PMID 29881878, 2018).
diabetes (continued). "Expression of T-bet helps slow the progression of diabetes in NOD mice, as it is required for Tregs to express the chemokine CXCR3 that enables migration to the pancreas." (PMID 39704171, 2024). "On diabetes antigen-(IGRP) specific T cells in the pLNs, we likewise found reduced expression of CXCR3." (PMID 34417463, 2021). "A parallel analysis of CD3+ T cells revealed that CXCR3 expression was reduced in four of the eight areas identified by SPADE in individuals with long-standing diabetes vs healthy donors (areas 2, 4, 5 and 6: p < 0.005 in Study A, p < 0.005 in Study B)." (PMID 29881878, 2018). "Blockade of CXCR3 with ACT-777991 monotherapy was not efficacious in inducing diabetes remission in both mouse models versus isotype-treated animals (data not shown for the RIP-LCMV-GP model)." (PMID 37458220, 2023). "We therefore suggest that the lack of statistical significance in one of the newly diagnosed cohorts was due to a small sample size, rather than a change in CXCR3 expression limited to individuals with long-standing diabetes." (PMID 29881878, 2018). "However, these chemokine receptors are responsible for the recruitment of both diabetogenic and protective cells as revealed by the reduced incidence of diabetes observed in the CCR2−/− NOD mice and the accelerated incidence in the CXCR3−/− or the CCR5−/− NOD mice." (PMID 24968718, 2014).
pulmonary fibrosis (19 papers, 2005 to 2025). Chronic progressive interstitial lung disorder characterized by the replacement of the lung tissue by connective tissue, leading to progressive dyspnea, respiratory failure, or right heart failure. "In murine models of bleomycin-induced pulmonary fibrosis, CXCR3 deficiency resulted in loss of NK cell recruitment to the lung and subsequent IFN-γ production resulting in increased pulmonary fibrosis." (PMID 31354734, 2019). "CXCR3-/- mice deficient mice developed less severe pulmonary fibrosis, inflammation, and cytokine levels, which was associated with a deficiency in NK cell migration to the lung and airways." (PMID 24922516, 2014). "Additionally, polymorphisms in the genes encoding chemokine (C-C motif) ligand 18 (CCL18) and chemokine (C-X-C motif) receptor 3 (CXCR3) have been linked to CS-induced pulmonary fibrosis." (PMID 37371940, 2023). "The bronchoalveolar lavage samples of adults with idiopathic pulmonary fibrosis exhibit comparatively less CXCR3+ cells than healthy controls, supporting a critical role for CXCR3 in chronic lung diseases." (PMID 34682144, 2021). "Patients with dSSc and those with lung fibrosis revealed higher anti-CXCR3 and anti-CXCR4 ab levels compared with those with lSSc and without SSc-ILD." (PMID 29566745, 2018). "An increased reactivity of abs against an N-terminal fragment of CXCR3 correlated with a more benign progression of lung fibrosis in SSc in an earlier study." (PMID 29623076, 2018). "Our findings are consistent with the suppression of CXCL-9 by IL-22 in an animal model of lung fibrosis which limited recruitment of CD4+CXCR3+ T cells and attenuation of lung inflammation and fibrosis." (PMID 29163483, 2017). "In a mouse model of pulmonary fibrosis (bleomycin-induced), the disease is more severe in mice where CXCR3-dependent immune cell (particularly NK cell) recruitment is reduced, resulting in increased mortality in Cxcr3-/- animals." (PMID 35844626, 2022). "Interestingly, both CXCL9 and CXCL10 but not CXCL8, exert their effects via chemokine receptor CXCR3, and CXCR3-deficient mice are known to develop progressive interstitial pulmonary fibrosis." (PMID 27127180, 2016). "All three chemokines are ligands for CXCR3, recruit CD4+ Th1 cells and CD8+ T cells to the site of tissue injury, and inhibit angiogenesis during pulmonary fibrosis." (PMID 37493737, 2023). "Here, anti-CXCR3 and anti-CXCR4 ab levels are shown to be very good markers of predicting lung fibrosis and are, therefore, candidates to stratify patients for disease progression, e.g., in clinical studies." (PMID 29566745, 2018). "Frequencies and median fluorescence intensities (MFI) of CXCR3+ and CXCR4+ PBMCs were lower in SSc patients compared with HD and correlated with the severity of skin and lung fibrosis." (PMID 29566745, 2018). "Because of the role of CXCR3 expression in the migration of T cells, strategies to block CXCL10 could in theory be proposed to prevent the development of HP reactions, particularly in subjects continuously exposed to inhaled antigens and thus at risk for the development of lung fibrosis." (PMID 15725351, 2005). "Exogenous administration of IFNγ has been shown to be critical for limiting lung fibrosis in CXCR3 knockout mice lacking endogenous IFNγ." (PMID 20302663, 2010).
renal cell carcinoma (18 papers, 2014 to 2025). "Compared with normal renal tissue, the mRNA expression of CXCR3/CXCL9/10/11 in renal cell carcinoma was significantly increased, and the upregulation of CXCR3 expression in renal cell carcinoma was related to the hypoxic state in TME." (PMID 39372416, 2024). "In patients with renal cell carcinoma, 5-year disease-free survival was significantly better in patients with low CXCR3-expressing tumors." (PMID 36479091, 2022). "CXCR3 is involved in renal cell carcinoma cell migration, invasion, and clonogenic ability, and decreased CXCR3 expression is correlated with worse prognosis in patients with renal cell carcinoma." (PMID 31696204, 2019). "High expression levels of CXCR2 and CXCR3 in cancer tissues correlated with tumour progression of renal cell carcinoma." (PMID 27297979, 2016). "The aim of our study therefore was to evaluate occurrence of CXCR3 in tissue samples, to analyse its expression in higher tumor grades and stages and to interpret the results to designate CXCR3 as a potential marker for predicting recurrence in renal cell carcinoma after primary surgical resection." (PMID 36831346, 2023). "However, future studies should aim to confirm the clinical and prognostic role of CXCL9–11/CXCR3 in renal cell carcinoma." (PMID 33202536, 2020). "The up-regulation of CXCR3 involves the inhibition of angiogenesis in renal cell carcinoma." (PMID 31696204, 2019). "The importance of the CXCR3/CXCR3 ligand biological axis for inhibiting tumor growth has been substantiated in renal cell carcinoma (RCC)." (PMID 32089645, 2020). "In renal cell carcinoma, CXCR3 may selectively recruit T cells to the tumour." (PMID 24961933, 2014). "The ratio of CXCR3-A to CXCR3-B is higher in renal cell carcinoma (RCC) tissues compared to normal kidney tissues, and the total expression of CXCR3 and CXCR3-A is significantly higher in metastatic RCC tissues than in non-metastatic RCC tissues." (PMID 40786052, 2025). "Sporadic instances of renal cell carcinomas in humans exhibit heightened expression levels of CXCL9, CXCL10, and CXCL11, hence facilitating the recruitment of T cells that possess CXCR3 and CCR5 receptors." (PMID 38730579, 2024). "In contrast, in renal cell carcinoma and chronic lymphocytic leukemia (CLL), low CXCR3 expression implies a shorter survival time for patients." (PMID 36479091, 2022). "Therefore, the aim of this study was to carry out a review of the current literature regarding chemokine receptor 3 (CXCR3) and its ligands, to determine their clinical significance and role in the pathogenesis of renal cell carcinoma." (PMID 33202536, 2020). "In renal cell carcinoma (RCC), tumor-infiltrating CD4+ T cells were found to predominantly express both CCR5 and CXCR3, supporting a Th1-polarized immune infiltrate." (PMID 40475782, 2025).
asthma (16 papers, 2009 to 2026). "A CXCR3-dependent amplificatory mechanism also aligns with the association of airway CXCL10 expression with an IFN-γ–high asthma phenotype in human subjects and mice." (PMID 31445933, 2020). "Clinical research has indicated that the number of CXCR3+ T cells in blood sampled from asthmatic patients was elevated, and this elevation was associated with asthma severity." (PMID 27727269, 2016). "Increased numbers of CXCR3+ T cells in blood have been reported to be associated with asthma severity." (PMID 21939519, 2011). "Moreover, health outcome association analysis linked the accumulation of these unique CXCR3- central memory CD8 T cells to asthma, chronic liver conditions, and type 2 diabetes." (PMID 41622514, 2026). "Thus, the increased numbers of CXCR3+ T cells in blood was reported to be associated with asthma severity." (PMID 21939519, 2011). "It remains very difficult to predict the effect of intronic variants but that does not mean that they do not have an effect; it has, for example, been shown that a common intronic variant in the chemokine receptor gene CXCR3 is associated with gene expression levels and asthma risk." (PMID 19837565, 2009). "Ruxolitinib’s potent inhibition of CXCL10 production is an important finding because this chemokine recruits Th1 cells via the cognate receptor CXCR3 and thus contributes significantly to Th1-high asthma and failure to respond to corticosteroids." (PMID 36059986, 2022). "CXCL9 and CXCL10, which have been shown to be induced in other mouse models of asthma and A. fumigatus-induced inflammation (34, –, 36), activate Th1-type immune responses through CXCR3." (PMID 33597172, 2021). "This study aimed to assess the specific effects of CXCR3 in a model of HDMP-induced asthma in CXCR3 knockout (CXCR3KO) mice." (PMID 27727269, 2016). "There is considerable evidence for the role of CXCR3 and CXCR3-binding ligands in many acute and chronic inflammatory and autoimmune diseases, such as asthma, rheumatoid arthritis, multiple sclerosis, and psoriasis." (PMID 24223818, 2013). "The observations presented in this study point to an important role for CXCR3 in a murine allergic model of asthma." (PMID 21939519, 2011). "Our data are consistent with previous reports that also support the importance of CXCR3 in the initiation and progression of airway inflammation in asthma." (PMID 21939519, 2011). "An interaction of CXCL10/CXCR3 has been reported to contribute to the migration of mast cells into airway smooth muscle in asthma." (PMID 21939519, 2011). "In this study, we investigated the specific contribution of CXCR3 in a model of ovalbumin (OVA)-induced asthma using CXCR3 KO mice and WT mice as control." (PMID 21939519, 2011). "Elucidation of the precise role of CXCR3 in asthma has been facilitated by the generation of CXCR3 knockout (KO) mice." (PMID 21939519, 2011). "Eosinophilic inflammation in patients with CRSwNP (as well as those with asthma) is also regulated by T2 cytokines that induce epithelial cells to produce eotaxins, which recruit eosinophils to the airway via chemokine receptor 3 (CXCR3) binding." (PMID 40919679, 2025). "In addition, we only measured the serum concentration of CXCL10 in asthma patients, the most studied and important for asthma pathogenesis among three CXCR3 chemokines." (PMID 37029363, 2023). "In addition, the interaction of CXCL10 with CXCR3 has been reported to contribute to mast cells migration into airway smooth muscle in asthma." (PMID 27727269, 2016). "CXCR3, a Th1-type cell receptor, plays an important role in immune system regulation in asthma." (PMID 27727269, 2016). "Promoting the expression of CXCR3 and its ligands may represent a novel therapeutic approach for preventing and curing asthma." (PMID 27727269, 2016). "Promoting the expression of CXCR3 and its ligands in T cells may represent a novel prevention and treatment strategy for asthma." (PMID 27727269, 2016).
asthma (continued). "CXCL10 may also mediate CXCR3+T lymphocyte recruitment to the ASM in severe asthma and following allergen challenge." (PMID 24648846, 2014). "However MC in the ASM of people with asthma are CXCR3 positive, whereas less than half of the MC elsewhere in the airway submucosa express CXCR3." (PMID 24648846, 2014). "Data from mouse models of asthma suggest that increases in recruitment of CXCR3+ T cells homing to the lung may increase the severity of asthmatic response." (PMID 21939519, 2011). "Our findings suggest that designing an inhibitor specially targeting CXCR3 may be helpful for the treatment of asthma." (PMID 21939519, 2011). "Taken together, these findings indicate that CXCR3/CXCL10 axis may play a pivotal role in the pathogenesis of asthma through recruitment of T cells, as well as other inflammatory cells, into airways and lung parenchyma." (PMID 21939519, 2011). "In the present study, we investigated the role of CXCR3 and its ligands in airway inflammation induced by house dust mite protein (HDMP) in a CXCR3 knockout (CXCR3KO) asthma mouse model." (PMID 27727269, 2016). "In asthma, the ASM produces the chemokine CXCL10 which we have previously shown induces MC chemotaxis through CXCR3 engagement." (PMID 24648846, 2014). "Thus, blockade of CXCR3 may represent a novel target for asthma treatment." (PMID 21939519, 2011). "Pathways exclusively enriched in AD included Cytokines and Inflammatory Responses, Th1/Th2 Differentiation, Dendritic Cell Pathway, Asthma, IL-12 STAT4 Signaling, CD40L Signaling, IL-4 Signaling, and CXCR3 Signaling, IL-2 STAT5 Signaling, CD8+ T-cell Signaling, and TCR Signaling." (PMID 28821884, 2017). "In asthma, the airway smooth muscle (ASM) produces CXCL10 which may attract CXCR3+ mast/T cells to it." (PMID 24648846, 2014). "Furthermore, a two-week course of oral prednisolone did not change the number of peripheral blood CXCR3+ T cells in asthma patients." (PMID 21939519, 2011).